CDK7 (cyclin dependent kinase 7)
Description:
Serine/threonine kinase involved in cell cycle control and in RNA polymerase II-mediated RNA transcription. As a cyclin-dependent kinase, CDK7 is activated by the binding to cyclin-H/CCNH and the CDK-activating kinase assembly factor MAT1. Catalytic subunit of the CDK-activating kinase (CAK) complex, a master regulator of CDK activity by catalyzing the activating threonine phosphorylation of CDKs. CAK activates major mediators of cell cycle control, including CDK1, CDK2, CDK4 and CDK6, and plays a key role in regulating cell cycle progression. CAK complexed to the core-TFIIH basal transcription factor activates RNA polymerase II by serine phosphorylation of the CTD of POLR2A, allowing its escape from the promoter and elongation of the transcripts. Initiates transcription by RNA polymerase II by mediating phosphorylation of POLR2A at 'Ser-5' of the repetitive C-terminal domain (CTD) when POLR2A is in complex with DNA, promoting dissociation from DNA and initiation. Its expression and activity are constant throughout the cell cycle. Required for DNA-bound peptides-mediated transcription and cellular growth inhibition.
Synonyms: CAK; CAK1; CDKN7; MO15; STK1; HCAK; p39MO15
Tractability: Small molecule: a drug acting on it is in phase 2 or 3 trials; a structure with a bound ligand is known; a high-quality ligand is known; it has a high-quality binding pocket; it belongs to a druggable protein family. Antibody: its Gene Ontology location is reachable by antibodies, with high confidence. PROTAC: it is named in the literature on targeted protein degradation; ubiquitination databases record sites on it; its protein half-life has been measured; a small molecule that binds it is known.
Target class: CMGC protein kinase CDK7 subfamily; Enzyme; CMGC protein kinase group; Protein Kinase; Kinase; CMGC protein kinase CDK family
Chemical probes: JNJ-3738 (high quality), THZ1 (high quality), YKL-01-116 (high quality), YKL-5-124 (high quality)
Safety:
Unwanted effects reported when the protein is acted on. In parentheses: how it was acted on, where the effect was seen, and who reports it.
cardiac arrhythmia (cardiovascular system; source: Lamore et al. (2017))
Gene: Protein-coding gene on chromosome 5 (69,234,795 to 69,277,430, forward strand). Ensembl gene ENSG00000134058.
Subcellular location: Nucleus; Cytoplasm; Cytoplasm, perinuclear region
Subcellular location (Human Protein Atlas): Nucleoplasm; Cytosol; Nucleoli fibrillar center; Plasma membrane
Pathways (Reactome):
Gene expression (Transcription): Formation of RNA Pol II elongation complex; Formation of the Early Elongation Complex; NoRC negatively regulates rRNA expression; RNA Pol II CTD phosphorylation and interaction with CE; RNA Polymerase I Promoter Escape; RNA Polymerase I Transcription Initiation; RNA Polymerase I Transcription Termination; RNA Polymerase II Pre-transcription Events; RNA Polymerase II Promoter Escape; RNA Polymerase II Transcription Elongation; RNA Polymerase II Transcription Initiation; RNA Polymerase II Transcription Initiation And Promoter Clearance; RNA Polymerase II Transcription Pre-Initiation And Promoter Opening; RNA polymerase II transcribes snRNA genes; RUNX1 regulates transcription of genes involved in differentiation of HSCs
Disease: Formation of HIV elongation complex in the absence of HIV Tat; Formation of HIV-1 elongation complex containing HIV-1 Tat; Formation of the HIV-1 Early Elongation Complex; HIV Transcription Initiation; RNA Pol II CTD phosphorylation and interaction with CE during HIV infection; RNA Polymerase II HIV Promoter Escape; Tat-mediated elongation of the HIV-1 transcript; Transcription of the HIV genome
DNA Repair: Dual incision in TC-NER; Formation of Incision Complex in GG-NER; Formation of TC-NER Pre-Incision Complex; Gap-filling DNA repair synthesis and ligation in TC-NER; Transcription-Coupled Nucleotide Excision Repair (TC-NER)
Cell Cycle: Cyclin A/B1/B2 associated events during G2/M transition; Cyclin A:Cdk2-associated events at S phase entry; Cyclin D associated events in G1; Cyclin E associated events during G1/S transition
Metabolism of RNA: mRNA Capping
Gene Ontology:
Molecular function: ATP-dependent activity, acting on DNA; protein binding; protein serine kinase activity; RNA polymerase II CTD heptapeptide repeat kinase activity; RNA polymerase II CTD heptapeptide repeat S5 kinase activity; cyclin-dependent protein serine/threonine kinase activity; protein kinase activity; protein serine/threonine kinase activity; ATP binding; kinase activity
Biological process: positive regulation of transcription by RNA polymerase II; protein stabilization; regulation of G1/S transition of mitotic cell cycle; transcription initiation at RNA polymerase II promoter; nucleotide-excision repair; regulation of cell cycle; snRNA transcription by RNA polymerase II; transcription by RNA polymerase II
Cellular component: CAK-ERCC2 complex; cyclin-dependent protein kinase holoenzyme complex; cytoplasm; cytosol; fibrillar center; nucleoplasm; nucleus; transcription factor TFIIH core complex; transcription factor TFIIH holo complex; transcription factor TFIIK complex; perinuclear region of cytoplasm
Genetic constraint (gnomAD): Loss-of-function variants: 7 observed, 16.99 expected, observed/expected ratio (o/e) 0.41, 90% interval 0.23 to 0.77. The upper end of that interval is the gene's LOEUF score, 0.77, which puts it in group 3 of 6, group 1 being the genes least tolerant of losing a copy. Missense variants: 142 observed, 172.17 expected, observed/expected ratio (o/e) 0.82, 90% interval 0.72 to 0.95. Synonymous variants: 53 observed, 65.23 expected, observed/expected ratio (o/e) 0.81, 90% interval 0.65 to 1.02.
Homologues: Orthologues: chimpanzee CDK7 (100% identical), macaque CDK7 (99% identical), dog CDK7 (97% identical), rabbit CDK7 (97% identical), pig CDK7 (95% identical), mouse Cdk7 (95% identical), guinea pig CDK7 (93% identical), rat Cdk7 (90% identical), tropical clawed frog cdk7 (86% identical), zebrafish cdk7 (86% identical), Drosophila melanogaster Cdk7 (67% identical), Caenorhabditis elegans cdk-7 (56% identical). Paralogues in human: CDK11A (40% identical), CDK11B (40% identical), CDK1 (39% identical), CDK10 (39% identical), CDK16 (39% identical), CDK3 (39% identical), CDK2 (39% identical), CDK12 (38% identical), CDK19 (38% identical), CDK5 (38% identical), CDK18 (38% identical), CDK13 (38% identical), and 14 more.
Diseases named in the same sentence as CDK7 in open-access papers:
CDK7 is named in the same sentence as 124 diseases in open-access papers, as found by Europe PMC text mining. Sharing a sentence is not in itself a finding about the gene and the disease. The quoted sentences say what the papers report.
breast carcinoma (60 papers, 2010 to 2025). "SY-1365, a modified variant of THZ1 and a CDK7 inhibitor, started its phase I clinical trial for the treatment of ovarian and breast carcinomas in 2017." (PMID 38786326, 2024). "In breast cancer, a high expression of CDK7 mRNA was linked to a poorer prognosis, while overall CDK7 protein expression showed no significant prognostic link." (PMID 38037549, 2023). "CDK7 is a transcriptional cyclin dependent kinase that has been implicated in a number of breast cancer subtypes and CDK7 overexpression is associated with poor prognosis in TNBC." (PMID 37190140, 2023). "We also searched existing publications but found few studies demonstrating an association between certain common genomic alterations in breast cancer and CDK7." (PMID 36058938, 2022). "High ectopic expression of CDK7 has been detected in multiple types of cancers, including gastric cancer, oral squamous cell carcinoma, and breast cancer, and is associated with aggressive clinicopathological features and poor prognosis." (PMID 34490348, 2021). "In turn, survival analysis indicated that higher mRNA expression of CDK7 was significantly associated with inferior RFS in breast cancer patients." (PMID 33686962, 2021). "In particular, overexpression of cyclin-dependent kinase 7 (CDK7) has been reported in breast cancer and is highly associated with poor prognosis." (PMID 34490348, 2021). "High CDK7 RNA levels correlated with worse RFS for all breast cancer patients, with the strongest associations found in basal (p = 1.4 × 10−05, HR = 1.75) and HER2+ (p = 9.5 × 10−05, HR = 1.91) subgroups." (PMID 32155786, 2020). "CDK7 is highly expressed in breast cancer and is associated with poor prognosis and is correlated with poor response to endocrine treatment." (PMID 32340192, 2020). "High expression of CDK7 (first sextile) was associated with significantly shorter overall survival (OS) for only ER+ breast cancer patients (p = 0.01)." (PMID 32340192, 2020). "Kaplan-Meier (KM) plots show that high CDK7 expression is associated with worse Relapse Free Survival (RFS) in an unselected cohort of breast cancer patients representing multiple different subtypes of breast cancer (p =2.5 × 10−05, HR = 1.40)." (PMID 32155786, 2020). "Because its dysfunction could induce malignant tumors such as breast cancer, CDK7 inhibitors including flavopiridol, roscovitine, and THZ1 are important anti-tumor drugs." (PMID 38640110, 2024). "This program could be disrupted by inhibiting CDK7, which represents a potential therapeutic option for breast cancer, especially estrogen receptor (ER) mutation-mediated endocrine-resistant type." (PMID 33926574, 2021). "Also, the sensitivity of breast cancer cells to CDK7 inhibitors appears to be associated with the loss of ER and Rb1 CN expression." (PMID 34123801, 2021). "In a clinical sample, CDK7 was associated with good response to tamoxifen in breast cancer patents." (PMID 32340192, 2020). "The polymorphisms of CDK7 are known to effect breast cancer." (PMID 25349887, 2014). "Dual treatment combining HER2-targeted therapy (Lapatinib) with the CDK7 inhibitor THZ1 strongly inhibits HER2+ breast cancer cell growth and increases apoptosis in cancer cells that exhibit resistance to HER2-targeted therapies." (PMID 39800748, 2025). "In preclinical settings, CDK7 inhibitors have demonstrated potential in overcoming resistance in breast cancer." (PMID 40949156, 2025). "In this sense, it is also worth mentioning that a recent study demonstrated CDK7 as a putative vulnerability to overcome CDK4/6 resistance in breast cancer." (PMID 41193441, 2025).
breast carcinoma (continued). "According to the literature, CDK7 has also emerged as a promising target in different molecular types of breast cancer, including TNBC." (PMID 41463161, 2025). "The first highly-selective CDK7 inhibitor, BS-181, suppressed growth of breast cancer mice xenografts in vivo." (PMID 40163908, 2025). "CDK7 and ER mRNA levels were found to positively correlate in TCGA ER-positive (ER+) breast cancer samples, and patients with ER+ breast cancer who express high levels of CDK7 have a noticeably lower overall survival." (PMID 40361480, 2025). "Analysis of TCGA and GTEx databases revealed that CDK7 mRNA expression is the lowest among the four breast cancer subtypes, however, it remained significantly higher than that in normal breast tissues." (PMID 39656925, 2025). "In keeping with this finding, in previous studies, we identified CDK7 as a potential therapeutic target in ER+ breast cancer, and selective CDK7 inhibitors are currently in clinical development in metastatic HR+ breast cancer." (PMID 40327396, 2025). "It is interesting to note that TNBC cells were more sensitive to CDK7 inhibition than HR+ breast cancer cells." (PMID 40361480, 2025). "Preclinical studies of the CDK7 inhibitor CT7001 in breast cancer models provided evidence that combining CT7001 with tamoxifen (hormonal therapy) resulted in better antitumour activity compared to CT7001 alone." (PMID 40163908, 2025). "Analysis of TCGA ER-positive (ER+) breast cancer samples has revealed a positive correlation between CDK7 and ER mRNA levels, and high CDK7 expression has been associated with notably shorter OS for ER+ breast cancer patients." (PMID 38605321, 2024). "A comprehensive understanding of the direct impacts of CDK7 inhibition on both stromal and immune cells is imperative for nuanced analysis within the framework of breast cancers." (PMID 38605321, 2024). "Analyzing breast cancer TMAs for CDK7 (n = 945), the study found that patients with high-grade and extensive tumors, or those with recurrent disease, exhibited lower CDK7 expression." (PMID 38605321, 2024). "Recent advancements have ushered in a cadre of CDK7 inhibitors into phase I/II clinical trials for breast cancer." (PMID 38605321, 2024). "Subsequent investigations have been conducted to elucidate the underlying mechanisms of acquired resistance to CDK7 inhibitors, ICEC0942 and THZ1, within the context of breast cancer treatment." (PMID 38605321, 2024). "Although the efficacy of CDK7 inhibition in endocrine-resistant, palbociclib-resistant breast cancer is currently being investigated, little is known as to the potential of targeting the transcriptional regulator CDK9 in ER+ breast cancers." (PMID 37801608, 2024). "In this comprehensive review, we illuminate the multifaceted role of CDK7 in maintaining malignant phenotypes and fostering drug resistance across diverse molecular subtypes of breast cancer." (PMID 38605321, 2024). "The specific CDK7 small molecular inhibitors have yielded promising results in suppressing malignant phenotypes across over 23 cancer types, especially in breast cancer." (PMID 38605321, 2024). "This review delineates the biological roles of CDK7 and explicates the molecular pathways through which CDK7 exacerbates the oncogenic progression of breast cancer." (PMID 38605321, 2024). "This landscape of disparate findings illustrates the complexity of CDK7’s role within breast cancer prognosis and highlights the necessity for further refined and targeted investigations." (PMID 38605321, 2024). "The accumulated evidence substantiates the conceptualization of CDK7 as a propitious therapeutic target in breast cancer management." (PMID 38605321, 2024). "The specific CDK7 inhibitors are predominantly assessed in patients with locally advanced or metastatic HR+/HER2- breast cancer, who exhibited failure in prior treatment with a CDK4/6 inhibitor in combination with hormonal therapy." (PMID 38605321, 2024).
breast carcinoma (continued). "CDK7 expression has also recently been reported to be a candidate biomarker for poor prognosis in breast cancer." (PMID 37201585, 2023). "Previous studies involving leukemia and breast cancer models have revealed that CDK1 relies more on CDK7-mediated activation activity and stability, while other CDK-activating kinases can also regulate CDK2, in addition to CDK7." (PMID 37507802, 2023). "AUR102 is a recently described orally bioavailable CDK7-selective inhibitor with preclinical activity in models of breast cancer, prostate cancer, and lymphoma." (PMID 35568739, 2022). "Estradiol induces transcriptional activation/expression of the PRLR gene, and subsequent studies revealed the essential role of autocrine PRL released by breast cancer cells and CDK7 in estradiol-induced PRLR promoter activation and upregulation." (PMID 36187116, 2022). "Preclinical studies of CT7001 in breast cancer models provided evidence that the combination of CDK7 inhibitors with tamoxifen is superior to either monotherapy." (PMID 35568739, 2022). "The most impressive feature is that CDK7 inhibition not only prejudices the cell growth of breast cancer, but also the resistance of the estrogen-responsive MCF7 breast cancer cells." (PMID 33926574, 2021). "To explore the effect of CDK7 inhibitors on breast cancer cells, we measured the viability of MCF-7 cells after incubation with increasing concentrations of THZ1 and LDC4297 for 24 and 48 h." (PMID 34490348, 2021). "Our study aimed to explore a novel mechanism of CDK7 inhibition for suppressing breast cancer cell survival." (PMID 34490348, 2021). "In our study, analysis of Oncomine and HPA datasets revealed that CDK7 expression was significantly higher in breast cancer than in normal breast tissue." (PMID 33686962, 2021). "The repression of breast cancer cell proliferation and colony formation was observed following CDK7 inhibition treatment, identifying CDK7 inhibitors as potential agents for breast cancer treatment." (PMID 34490348, 2021). "We further explored the mechanisms that contributed to the different sensitivities of different breast cancer cells to CDK7 inhibition." (PMID 34109118, 2021). "It has been demonstrated that CDK7 overexpression occurred in the estrogen receptor-positive, palbociclib-resistant breast cancer cells, suggesting that CDK7 is involved in cellular resistance to CDK4/6 inhibitors." (PMID 34123801, 2021). "CDK7 inhibitors have emerged as promising drugs for treating diverse cancers, including breast cancer." (PMID 34109118, 2021). "At the mRNA level, overexpression of CDK7 or CDK8 was associated with inferior prognosis, whereas higher CDK13 expression was associated with favorable prognosis in breast cancer patients." (PMID 33686962, 2021). "Higher cyclin-dependent kinase (CDK7) expression is a character of breast cancer and indicates poor prognosis." (PMID 34490348, 2021).